TNF (tumor necrosis factor)
Diseases named in the same sentence as TNF in open-access papers (continued):
Sharing a sentence is not in itself a finding about the gene and the disease.
Obesity (continued). "Adipose tissue in obesity functions as an endocrine organ, secreting pro-inflammatory cytokines such as tumor necrosis factor-alpha (TNF-α), interleukin-6 (IL-6), and leptin while suppressing anti-inflammatory adiponectin levels." (PMID 40243559, 2025). "By secreting inflammatory molecules such as IL-6, IL-1β, and TNF-α, macrophages drive inflammation, exacerbating obesity, insulin resistance, and type 2 diabetes." (PMID 40453651, 2025). "Among the proinflammatory cytokines discussed, IL-6, CRP, and TNF-α appear to be the most promising candidates as potential biomarkers for depression, particularly in the context of obesity, where their levels are also elevated." (PMID 40507778, 2025). "Obesity activates various proinflammatory pathways, which includes elevated level of cytokines such as tumor necrosis factor-α (TNF-α), interleukin-6 (IL-6), C-reactive protein (CRP), plasminogen activator inhibitor-1 (PAI-1), and leptin." (PMID 40893881, 2025). "Increased systemic TNF-α in obesity leads to increased activity of IKK, p38 MAPK, JNK, and PKC proteins, which modify IRS protein serine residues and hinder tyrosine phosphorylation, causing insulin resistance in adipose tissues, muscles, and the liver." (PMID 40141412, 2025). "In individuals with obesity or MetS, Breg cells tend to reduce the number of IL-10 secreting cells, increase autoantibody production, and increase the number of TNF-α and IL-6-producing cells." (PMID 40696355, 2025). "Few measures against pro-inflammatory cytokines are administered in treating obesity-related SAP; thus, we applied anti-TNFα therapy in mice models of obesity-related SAP." (PMID 39856555, 2025). "A notable proportion of network hubs—including FXR, GPBAR1, IL6, and TNF—were shared across multiple disease pathways, emphasizing the relevance of probiotic metabolites in modulating conditions such as type 2 diabetes, obesity, NAFLD, and IBD." (PMID 40612394, 2025). "In obesity, increased TNF-α and free fatty acids (FFAs) lead to chronic activation of JNK (c-Jun N-terminal kinase) in the liver, muscle, and adipose tissues." (PMID 40871683, 2025). "Adipocytokines are immunomodulatory proteins secreted by adipocytes that act in feedback loops linking obesity and cardiometabolic disease, which typically include leptin, adiponectin, interleukin (IL)-6, IL-18, and tumor necrosis factor-alpha (TNF-a)." (PMID 40486661, 2025). "In obesity-associated CRC, NFκB is a critical regulator of inflammation through IL-6 production and TNFα activation." (PMID 39201522, 2024). "Obesity particularly increases the pro-inflammatory factors interleukin-1 (IL-1), IL-6, and tumor necrosis factor-alpha (TNFα), which in turn stimulate the liver to produce other cytokines." (PMID 38915014, 2024). "After 6‐week oral treatments with EWE, EAF and RES, PPAR‐γ and Adiponectin expressions increased significantly, while TNF‐α expression decreased, suggesting the modulation of obesity‐induced inflammation in adipose tissue." (PMID 39698791, 2024). "Anti‐inflammatory and antiobesity effects of carvacrol derivatives (CD1‐3) were investigated in vitro (3T3‐L1, WJ‐MSCs, and THP‐1 cell lines) by assessing the expression of obesity‐related proteins and reducing TNF‐α expression, respectively." (PMID 38726397, 2024). "Another aspect of the complex interplay involving CVD, T2D, and obesity is the escalation of inflammatory cytokines, notably interleukin‐6 (IL‐6) and tumor necrosis factor alpha (TNF‐α) within the serum." (PMID 38874882, 2024). "Increased inflammatory cytokines such as interleukin 6 and tumor necrosis factor alpha (TNFα) are hallmarks of obesity, and promote the secretion of hepatic C-reactive protein (CRP) which further induces systematic inflammation." (PMID 38742193, 2024).
Obesity (continued). "When adipocytes are enlarged due to obesity, the adipose tissue secretes inflammatory cytokines and chemokines such as tumor necrosis factor (TNF)-α, interleukin (IL)-6, and leptin, along with infiltration of immune cells, including macrophages." (PMID 38672461, 2024). "Despite this, there was no significant change in the inflammatory biomarker CRP, or the inflammatory cytokines IL-6 or TNFα, in agreement with other vitamin C/antioxidant intervention studies in obesity and diabetes." (PMID 38671852, 2024). "Aggregation of adipose tissue with weight gain and obesity leads to the release of adipocytokines, including leptin, tumor necrosis factor (TNF)-α, resistin adiponectin, angiotensinogen, and fatty acids." (PMID 38337589, 2024). "Obesity is related to chronic low-grade inflammation, with the production of proinflammatory adipokines, such as tumor necrosis factor-α (TNF-α), interleukin-6 (IL-6), leptin, monocyte chemoattractant protein-1 (MCP-1), and resistin." (PMID 38542788, 2024). "Obesity is regarded as a chronic low-grade inflammatory state, with adipocytes secreting adipokines and inflammatory factors like IL-6 and TNF-α, which promote cellular carcinogenesis." (PMID 39867555, 2024). "Obesity is characterized by excessive adiposity and elevated levels of pro-inflammatory adipokines, such as tumor necrosis factor alpha and interleukin-6, resulting in a chronic low-grade inflammatory state." (PMID 39458427, 2024). "The downregulation of PD-L1 is influenced by the inflammatory cytokines prevalent in obesity, such as TNF-α and IL-6, which can directly impact PD-L1 expression and function." (PMID 40729297, 2024). "Obesity leads to the release of pro-inflammatory substances like tumor necrosis factor alpha (TNF-α), interleukin-6 (IL-6), and C-reactive protein (CRP), which induce the generation of ROS, resulting in elevated oxidative stress." (PMID 39194738, 2024). "In obesity, pro-inflammatory cytokines, mainly interleukins IL-6, IL-1b and tumor necrosis factor α (TNF-α), are released and activate several serine kinases, including c-Jun N-terminal kinase (JNK) and extracellular signal-regulated kinase (ERK)." (PMID 39728000, 2024). "Changes in DNA methylation of TNF alpha may be both causal for changes in biological processes by differentially regulating gene expression and consequential in response to modified physiological or environmental factors including diet and disease, such as obesity or low-grade inflammation." (PMID 38542788, 2024). "Another approach for obesity modeling is to expose WAOs to TNF-α or co-culture them with macrophages under lipopolysaccharide (LPS) stimuli." (PMID 38505622, 2024). "Cytokines that are classically upregulated in obesity, such as TNFα, IL-6, and TGFβ, promote tumour cell proliferation and invasion, and possible tumour formation." (PMID 38248845, 2024). "Gokhan Hotamisligil and colleagues made the first observation that the expression of TNF was increased in various models of obesity and diabetes." (PMID 38672492, 2024). "Polysaccharide from Agrocybe cylindracea (ACP) has been found to ameliorate obesity in high-fat diet-induced obese mice by significantly reducing the levels of obesity-related TNF-α and IL-6." (PMID 39130633, 2024). "Obesity was associated with increased expression of miR-155, which is activated by Nuclear Factor-kappa/Tumor Necrosis Factor (BNF-κB/TNF-alpha)." (PMID 39468643, 2024). "Pregnant women with obesity and PE exhibit higher leptin levels, correlating with increased Tumor Necrosis Factor-Alfa (TNF-α), Interleukin 6 (IL-6), and C-reactive protein concentrations." (PMID 38750456, 2024). "Our findings indicate that several cytokines, including IL-5, IL-17A, IL-22, IL-33, TNF-α, leptin, and IL-10 were independently influenced by asthma and obesity." (PMID 39902293, 2024). "In the obesity group, mtDNA copy number correlated significantly only with LPS-stimulated TNF-α secretion (R = 0.585, р = 0.028)." (PMID 38572445, 2024).
Obesity (continued). "The relationship between obesity and ORG is facilitated by a network of various inflammation-associated cells (e.g., synaptophysin) and a series of inflammatory mediators (e.g., TNF-α and IL-6)." (PMID 39234117, 2024). "At baseline, obesity and steatosis were associated with increased serum concentrations of CRP, IL-6 and TNFα." (PMID 39200991, 2024). "Obesity is a systemic chronic metabolic inflammation, with upregulation of inflammatory markers such as tumor necrosis factor (TNF-α), interleukins (IL)-6, IL-1β, and CCL2 in the adipose tissue of obese individuals." (PMID 39050542, 2024). "The association between obesity and inflammatory parameters was verified, and it was observed that obesity groups 1 and 2 presented elevations in plasma concentrations of TNF-α and IL-6." (PMID 39408365, 2024). "Adipocytes also produce excessive inflammatory cytokines such as tumor necrosis factor-alpha (TNF-a), interleukin 6 (IL6), leptin, and visfatin, which are associated with obesity, IR, or CVD." (PMID 38256617, 2024). "The cytokine production capacity of children with obesity was higher for TNF, IL-1β, IL-6, IL-10, IL-1Ra, IL-12p70, MCP-1, RANTES, and MIP1α, but not IL-8, indicating an overall hyperresponsive state compared to controls." (PMID 38741712, 2024). "An increased secretion of IL-6, leptin, IGF-1, and TNFα in obesity promotes EMT and inflammation, and dampens the immune response." (PMID 38248845, 2024). "Obesity leads to an increased systemic inflammation, during which adipocytes release pro-inflammatory cytokines such as TNF-α, IL-6, and C-reactive protein." (PMID 39839130, 2024). "Against this background, the expression of key pro‐inflammatory factors, Leptin and TNF‐α and anti‐inflammatory proteins namely PPARγ and adiponectin in the adipose can be manipulated in favour of obesity reduction." (PMID 39698791, 2024). "Adipocytes and macrophages within adipose tissue secrete TNF-α and IL-6, which influence the relationship between obesity and periodontitis." (PMID 39310407, 2024). "What is the functional outcome of targeting IL-6 trans-signaling in the presence of other cytokines (IL-1β, TNF-α, and IL-18) in obesity?" (PMID 39125976, 2024). "TNF-α is one of the inflammatory cytokines secreted by macrophages, that plays an important role in the pathogenesis of atherosclerosis and obesity." (PMID 38572445, 2024). "Our study expands on these findings and demonstrates a reduction in HM pro-inflammatory cytokines (TNF-α and IL-8) from women with obesity who underwent a Mediterranean dietary intervention." (PMID 38544749, 2024). "Investigation of the inflammatory status of BAT documented an increase in immune responses in HFD-induced obesity conditions relative to some of the inflammatory markers tested here, such as TNF-α, IL-1β, and IL-6 cytokines." (PMID 38671836, 2024). "Obesity leads to the overexpression of inflammatory factors like TNF-α, resulting in a systemic inflammatory state." (PMID 39858415, 2024). "The key role of TNFα in obesity is supported by several disease models, where conditions can be improved in obese mice by manipulating either TNFα or the TNF receptors." (PMID 38892358, 2024). "In pregnant women, both obesity and diabetes increase pro-inflammatory cytokines and adipokines, such as TNF-α, IL-6, IL-1β, leptin, and resistin, which are involved in the inflammatory response." (PMID 39584800, 2024). "In conditions of chronic inflammation, such as obesity, IKKβ is activated by pro-inflammatory cytokines like TNF-α (tumor necrosis factor-alpha) and IL-6 (interleukin-6)." (PMID 38920999, 2024). "Although there is a significant amount of information regarding the involvement of TNF-α in obesity, the specific mechanisms via which it functions, particularly in the central nervous system (CNS), are not well comprehended." (PMID 39149648, 2024). "TNF-α also has a positive correlation with obesity and modulates leptin, as well as stimulates the production of IL-6 and CRP." (PMID 38734032, 2024).
Obesity (continued). "This is characterized by the elevated levels of inflammatory cytokines like TNF-α and IL-6, which are commonly found in obesity-induced chronic inflammation." (PMID 38892561, 2024). "TNF-alpha (TNFα) links obesity and insulin resistance by interfering with the early stages of insulin signaling." (PMID 39766314, 2024). "What is well established in humans is the increased presence of proinflammatory markers of inflammation such as IL-1β, TNF-α, and IL-6 within AT of individuals with obesity." (PMID 38206766, 2024). "Our results are consistent with those findings, which indicated the positive association of asprosin levels with TNF-α levels, and TNF-α levels in groups with obesity were significantly higher than the control in the included subjects." (PMID 38475734, 2024). "Studies in obese individuals also reported the association of obesity with IFN-γ, TNF-α, and interleukin proteins." (PMID 38541912, 2024). "Gut dysbiosis and subsequent changes in intestinal permeability and tight junction are direct manifestations of obesity that may have direct effects on brain health through increased peripheral and central inflammation caused by an excessive expression of pro-inflammatory cytokines (TNF α and IL-6)." (PMID 39199499, 2024). "It was also shown that LPS-stimulated TNF-α secretion was significantly higher in the obesity + CHD group than in the control group and in the group of patients with obesity." (PMID 38572445, 2024). "The initiation of inflammatory pathways and up-regulated cytokines like IL-1β, IL-6 and TNF-α also contribute to obesity and IR development." (PMID 38163110, 2024). "In the experimental setting, it has been shown that EMPA, by polarizing M2 macrophages, has the potential to modulate energy expenditure, inflammatory response (decreased TNFα levels and obesity‐induced chronic inflammation), and IR." (PMID 39554295, 2024). "The presence of inflammatory cytokines, including elevation in serum levels of IL-6 and TNF-ά, has been demonstrated in diabetes and obesity." (PMID 39513912, 2024). "Increased inflammation levels in obesity are indicated by elevated levels of serum cytokines including TNF-α and IL-6." (PMID 39728103, 2024). "Proinflammatory cytokines such as IL-17, IL-6, IL-1 and TNF-α are increased in psoriasis and numerous studies suggest that they play a pivotal role in developing type 2 diabetes, hypertension, dyslipidaemia, obesity, insulin resistance and their complications." (PMID 39720714, 2024). "Obesity is a chronic, low-grade inflammatory condition characterized by the release of pro-inflammatory cytokines from adipose tissue, including TNF-α, IL-6, and IL-17, which can impact treatment outcomes." (PMID 39768570, 2024). "For example, the inflammatory factor TNF-α promotes obesity and insulin resistance in mice and inhibits adipocyte differentiation primarily by activating TNFR1." (PMID 38672517, 2024). "Other proinflammatory markers should be assessed (IL-1, IL-6, TNFα, or Interferon) to completely characterize the picture of inflammation in patients with obesity." (PMID 40729297, 2024). "In the present study, we found a significant difference in the inflammatory markers TNF-α and IL-1β as compared to lean group with OW and OB groups; cats with OW and obesity had higher concentrations of these inflammatory markers." (PMID 39328456, 2024). "Knockout mouse models lacking TNF-α function show improved insulin sensitivity and glucose homeostasis, highlighting TNF-α′s role in modulating insulin action in obesity." (PMID 38606081, 2024). "At week 16, there were increases in inflammatory (TNF-α in adipose tissue) and obesity (serum leptin, serum L/A ratio) markers." (PMID 39598339, 2024). "Lymphatic contractile dysfunction has been demonstrated in animal models of aging, obesity, TNFα overexpression, iNOS activation, metabolic syndrome, and other conditions associated with chronic inflammation." (PMID 39075985, 2024).
Obesity (continued). "The balance between lipogenesis and lipolysis is disturbed in obesity due to adipose tissue inflammation and increased tumor necrosis factor alpha (TNFα) levels, which interfere with insulin signaling." (PMID 39063092, 2024). "Both TNFα and Il-1β were found to be able to influence insulin signaling, although it was also shown that circulating level of TNFα is lower than the effective concentration even in patients with obesity." (PMID 39004641, 2024). "Evidence suggests that chronic inflammation and enhanced pro-inflammatory cytokine levels in the bloodstream and tissues, like TNFα and IL6, are linked to obesity." (PMID 39019936, 2024). "Other studies provide evidence of an association between obesity and some inflammatory markers, such as interleukin-6 (IL-6), C-reactive protein (CRP), and tumor necrosis factor-α (TNF-α)." (PMID 38634087, 2024). "Nevertheless, administration with FLT, FBT, or orlistat for eight weeks significantly suppressed the liver’s TNF-α, IL-1β, and IL-6 expression levels (p < 0.05), thus alleviating the inflammation induced by obesity." (PMID 38254507, 2024). "Monocytes of lean people and people with obesity were activated with LPS for 4 hours to analyze TNF release or 16 hours to analyze IL-1ß, IL-6, and IL-8 release, and cytokine concentrations were analyzed in the supernatant." (PMID 39050851, 2024). "The elevated TNF-α in obesity is a vital factor to induce insulin resistance because TNF-α activates IKK, p38 MAPK, JNK, and PKC, which directly target serine residues of insulin receptor substrate (IRS)." (PMID 39268243, 2024). "The secretion of inflammatory cytokines such as IL-6 and TNF-α is increased in patients with obesity." (PMID 39199353, 2024). "Obesity is a low-grade inflammation characterized by increased production and secretion of inflammatory cytokines, such as interleukin-6 and tumor necrosis factor-α, which stimulate the liver to synthesize and release CRP into circulation." (PMID 39765954, 2024). "Obesity triggers the activation of macrophages, mast cells, and T lymphocytes, resulting in the production of various adipokines and cytokines like tumor necrosis factor-α (TNF-α), interleukins, and interferon-γ." (PMID 38873392, 2024). "Relevant meta-analyses emphasize the pivotal role of overweight or obesity in CA risk and elucidate that a high-fat diet may lead to an increase in circulating fatty acids, subsequently triggering inflammation and releasing TNF-α and IL-6, thereby promoting CA development." (PMID 38846540, 2024). "Consistent with this assumption, the circulating PGRN/TNF-alpha ratio turned out to be a predictive factor of the elevation of systolic blood pressure in obesity and hypertension." (PMID 39000486, 2024). "This metabolically harmful NK population expands in obesity and secretes tumor necrosis factor alpha (TNFα), which ignites low-grade inflammation, increases plasma IL-6 levels, and impairs insulin sensitivity." (PMID 38474057, 2024). "TNFα is a pro-inflammatory cytokine that is often proposed as an important cytokine in obesity, in asthma, and in NAFLD." (PMID 38999877, 2024). "Adipose tissue macrophages in obesity and type 2 diabetes increase TNF-α and IL-6 production in the events of a high amount of lipolysis." (PMID 38728367, 2024). "This brings into focus the complex interplay between obesity and diabetes and markers such as leptin, IL6, TNFα, and IGFs in elevating the risk of endometrial cancer." (PMID 38339282, 2024). "In participants with obesity, we observed significantly elevated inflammatory marker (TNF-α and IL-6), myeloperoxidase, leptin, and insulin levels (p < 0.05)." (PMID 39700087, 2024). "In obesity, adipocytes produce elevated amounts of leptin, TNF-α, IL-6, visfatin, and resistin, all of which further disrupt metabolic and inflammatory regulation." (PMID 39770983, 2024).